CCNE1 (cyclin E1)
Diseases named in the same sentence as CCNE1 in open-access papers (continued):
Sharing a sentence is not in itself a finding about the gene and the disease.
breast carcinoma (continued). "Our results suggested that miR-885-3p could suppress the proliferation of breast cancer cells, partially by suppressing the expression levels of CDK2/CCNE1 and CDK4/6/CCND1 and arresting the cell cycle in the G0/G1 phase." (PMID 35383130, 2022). "In addition, western blotting indicated that miR-885-3p suppressed the progression of breast cancer cells by downregulating the expression level of PCNA and the expression levels of CDK2/CCNE1 and CDK4/6/CCND1 (Student’s t test, p < 0.05)." (PMID 35383130, 2022). "In conclusion, CCNE1 and PLK1 were identified as potential antigens in breast cancer." (PMID 36393842, 2022). "CCNE1 and PLK1 were identified as potential antigens in breast cancer." (PMID 36393842, 2022). "Unlike high expression of cyclin E1, which is predictive of poor survival, 19q12 (CCNE1) amplification had no prognostic value for overall survival in BRCA1 mutated breast cancer." (PMID 34465787, 2021). "Then we performed experiments to confirm that SENP3-EIF4A1 expression was higher in TNBC than luminal-type breast cancer, which had significantly negative correlations with miR-195-5p expression and positive correlations with CCNE1 expression." (PMID 33791304, 2021). "For breast cancer cell lines, qRT-PCR and western blot analysis confirmed that CCNE1 expression was higher in MDA-MB-231 and SUM1315 (two TNBC cell lines) than other types of breast cancer cell lines (MCF-7, ZR-75-1, and T47D) and normal breast epithelial cell line (HBL-100)." (PMID 33791304, 2021). "Notably, higher levels of CCNE1 and MCM2 negatively correlated with poor survival of patients with breast cancer." (PMID 33228782, 2020). "Interestingly, the expression of CCNE1 and MCM2 was also significantly inhibited as Roquin1 increased in 1006 human breast cancer samples (Oncolnc.org/)." (PMID 33228782, 2020). "In addition, we found a significant inverse correlation between CCND1/E1 and SALL2 expression in various cancers, but most notoriously between CCNE1 and SALL2 in breast cancer." (PMID 29689621, 2018). "Whether a combination of both 19q12 ISH assay and protein expression analysis of Cyclin E1 and URI by IHC is suitable, similar to HER2 assessment in breast cancer, needs further investigation." (PMID 27582547, 2017). "Copy number aberrations (CNAs) in known breast cancer driver genes present in the PDTXs included gains/amplifications of MYC (78%), CCNE1 (34%), ZNF703 (25%), CCND1 (31%), MDM2 (25%), and ERBB2 (9%) and deletions of PTEN (41%), PPP2R2A (72%), CDKN2A (47%), and CDKN2B (47%)." (PMID 27641504, 2016). "Some regions statistically associated with grade III tumors in our study harbor genes either frequently amplified in aggressive breast cancer such as the oncogenes MYC (8q24) and CCNE1 (19q12) or already reported as deleted in breast tumors such as MTAP (9p21)." (PMID 25391423, 2015). "Cyclin E2 gene amplification, but not cyclin E1, has been recently defined as marker for poor prognosis in breast cancer, and appears to play a major role in proliferation and therapeutic resistance in several breast cancer cells." (PMID 25596745, 2015). "Interestingly, it has been reported that cyclin E2 can be an independent and better prognostic marker for some breast cancer subtypes (including luminal A and HER2 positive) when compared with cyclin E1." (PMID 25596745, 2015). "Taken together, our results suggest that UQCRFS1, POP4, C19ORF12, CCNE1 and C19ORF2 are overexpressed in primary breast cancers and/or breast cancer cell lines harbouring their amplification, and may constitute potential drivers of this amplicon." (PMID 22433433, 2012). "Here we demonstrate that CCNE1 siRNA silencing in breast cancer cells harbouring CCNE1 gene amplification, but not in those lacking this amplification, resulted in a significant arrest in G1." (PMID 22433433, 2012).
breast carcinoma (continued). "While cyclin E1-Cdk2 and cyclin E2-Cdk2 kinase activities are increased in breast cancer compared to normal tissue, cyclin E1 and E2 expression and kinase activity are not essential for proliferation of all cancer cell types." (PMID 20180967, 2010). "CCNE2 is also a component of three prognostic gene expression signatures that predict shorter metastasis-free survival or relapse-free survival of breast cancer patients, whereas CCNE1 does not feature in any of these signatures." (PMID 20180967, 2010). "Ninety genes belonging to the GO category of 'apoptosis', including members of the BAG family (BAG1, BAG2, BAG3), as well as members of the breast cancer 'proliferation signatures' (BUB1, PLK1, CCNE1, CCND1 and CCNB1) were also identified as up-regulated in our DTET." (PMID 17014703, 2006). "Furthermore, circACTN4 overexpression might upregulate the expression of CCNE1 and CDK4 through increasing AcH4 levels of MYC target genes, thereby promoting cell cycle progression and tumorigenesis in breast cancer." (PMID 40612865, 2025). "Furthermore, CCNE1 expression has been suggested to be a predictive biomarker, with high CCNE1 RNA expression correlating with decreased progression-free survival in patients with metastatic hormone receptor–positive, HER2-negative breast cancer receiving the CDK4/6 inhibitor Palbociclib." (PMID 38717153, 2024). "We hypothesized that CCND1 and CCNE1 activation could represent a mechanism for palbociclib resistance in HNSCC, considering recent clinical data showing high CCNE1 as worse clinical outcome for palbociclib-treated patients in breast cancer." (PMID 38954773, 2024). "In accord with these results, breast cancer gene array profiling indicated that elevated expression of KLF4 in both MCF10A and MCF7 breast cancer cell lines upregulates transcription of several oncogenes and cell cycle activators such as MAPK, EGF/EGFR, IGF1, CYCLIN D2, CDK1, and CYCLIN E1." (PMID 30613353, 2018). "In order to examine the effect of FBW7 on EglN2 protein levels in breast cancer cell lines, we downregulated FBW7 expression levels by two independent hairpins in breast cell line MDA-MB-453 with wild type FBW7 expression and found FBW7 depletion led to increased EglN2 and Cyclin E1 levels." (PMID 28036276, 2017). "Cyclin E1 is often expressed at high levels in the absence of increased cyclin D1, and in fact cyclin E1-Cdk2 activity is increased by estrogen in breast cancer cells primarily through disengagement of p21Waf1/Cip1 rather than transcriptional upregulation by cyclin D1." (PMID 20180967, 2010). "In breast cancer alone, up to 50% of patients with Rbness in the absence of RB1 genomic alterations harbored amplifications in PIK3CA, RB (CCND1 and CCNE1), and ER signaling modules (ESR1, FOXA1, and GATA3)." (PMID 40138429, 2025). "Moreover, re-expression of both Bcl-2 and Cyclin E1 almost fully restored tamoxifen-resistance when miR-15a/16 mimics were co-transfected, suggesting Bcl-2 and Cyclin E1 work synergistically to confer tamoxifen resistance in breast cancer cells, but not being redundant to each other." (PMID 26397135, 2015). "The over-expressed CCNE1, CLGN, NEK2, PTTG1 and RAD51, and the under-expressed ADAMTS1, FOS, FOSB, IL6 and ZFP36 in tumor cells are examples of breast cancer genes without differential promoter methylation between normal and tumor samples." (PMID 25706888, 2015). "Silencing of CCNE1, PLEKHF1, POP4, ZNF536 and TSHZ3 expression selectively reduced cell viability in cancer cells harbouring 19q12 gene amplification but had a significantly lower impact on the survival of breast cancer cells lacking amplification of this locus (t-test P < 0.05)." (PMID 22433433, 2012). "Moreover, primary breast cancers harbouring CCNE1 amplification were found to have higher levels of CDK2 mRNA expression, adjusted for proliferation using the mRNA levels of CCNB1, than breast cancers devoid of CCNE1 amplification (P = 0.02789, t-test, data not shown)." (PMID 22433433, 2012).
ovarian carcinoma (149 papers, 2009 to 2026). A malignant neoplasm originating from the surface ovarian epithelium. "Cyclin E1 (CCNE1) amplification is associated with poor prognosis of ovarian carcinomas across histological subtypes." (PMID 39994376, 2025). "In epithelial ovarian cancer, high Cyclin E1 expression is associated with poor prognosis, and strong nuclear Cyclin E1 serves as an independent predictor of worse PFS." (PMID 40862791, 2025). "In a similar manner, it has been shown in ovarian cancers that amplifications within the CCNE1 gene (encoding cyclin E1) demonstrate poor responsiveness to PARPi." (PMID 39135999, 2024). "For example, CCNE1 amplification has been associated with poor survival in patients with triple-negative breast cancer and ovarian cancer." (PMID 38717153, 2024). "HRP ovarian cancer cells are often characterized by genetic alterations in signaling pathways that contribute to cell cycle dysregulation, such as cyclin E1 (encoded by CCNE1) and cyclin dependent kinase (CDK) genes." (PMID 38894867, 2024). "Cyclin E1 overexpression was also associated with platinum resistance in another immunohistochemical study in 110 ovarian cancers." (PMID 38612869, 2024). "In ovarian carcinoma, CCNE1 amplification has been associated with resistance to platinum‐based chemotherapy and shorter overall survival." (PMID 36572991, 2023). "CCNE1 overexpression and gene amplification have both been associated with poor prognosis in triple negative breast cancer as well as epithelial ovarian cancer." (PMID 35792986, 2022). "Noteworthy, the gain at 19q12 was associated with genomic instability and poorer survival in ovarian cancer patients, and the amplification of CCNE1 has been found as a discriminating biomarker for first-line platinum-based chemotherapy." (PMID 35372049, 2022). "Recently, high-throughput sequencing of breast and ovarian tumours revealed that common oncogene amplifications (i.e. CCND1 encoding cyclin D1 in breast cancer and CCNE1 encoding cyclin E in ovarian cancer) rarely occur in tumours with BRCA1/2 gene mutations." (PMID 34389725, 2021). "In this large study of HGSC patients, we validate that separately assessed CCNE1 high‐level amplification and overexpression are significantly associated with higher risk of ovarian cancer specific death." (PMID 32391646, 2020). "Amplification or upregulated expression of CCNE1 is associated with poor prognosis in some tumors such as breast or ovarian cancer." (PMID 31998560, 2020). "MiR-424-5p inhibits CCNE1 expression (encoding cyclin E1) in ovarian cancer, and inhibits cell cycle by suppressing the E2F transcription factor 1 (E2F1)-RB transcriptional corepressor (PRb) pathway, which promotes apoptosis." (PMID 32960785, 2020). "Cyclin E1 amplification is a common and distinct driver of tumorigenesis in epithelial ovarian cancer (EOC) that is associated with poor response to standard of care upfront chemotherapeutic agents." (PMID 32380689, 2020). "Amplification of CCNE1 is associated with many cancer progressions including gastric cancer, bladder cancer, ovarian cancer and triple negative breast cancer and linked to poor prognosis." (PMID 32818316, 2020). "Despite the scarcity of studies investigating CCNE1 amplification as a predictive biomarker in ovarian cancer, other primary disease sites have linked cyclin E1 amplification with poor response to chemotherapy both in vitro and in vivo." (PMID 32380689, 2020). "CCNE1 amplification is mutually exclusive with BRCA1/2 mutations and correlates with cyclin E1 protein expression in ovarian cancer." (PMID 30665374, 2019). "Mutual exclusivity of BRCA1/2 mutation/deletion and CCNE1 amplification has been shown previously in ovarian cancers." (PMID 30665374, 2019).
ovarian carcinoma (continued). "Isolated lymph node relapse cases demonstrated greater tumor-infiltrating lymphocyte burden at diagnosis, but did not demonstrate significant enrichment or depletion of BRCA1/2 mutation or gain of CCNE1, both known to be prognostic in ovarian carcinoma." (PMID 31055034, 2019). "Previous studies in ovarian cancer patients described increased expression levels of cyclin E1 and an association with worse survival." (PMID 31060523, 2019). "The increased frequency of CCNE1 gain in patients with short survival time is consistent with its known association with poor prognosis in ovarian cancer." (PMID 30382883, 2018). "CCNE1 gene amplification-associated CCNE1 overexpression has been linked to the development of chemo-resistance in ovarian cancer." (PMID 26204491, 2015). "In the GBM data, the involved pathways include parts of the RB signaling and RTK signaling pathways (CDKN2B, CDK4; EGFR, NF1 ), and in the ovarian carcinoma data a recurrent mutated module related to cell cycle and DNA repair (CCNE1, MYC, RAD52 ) is revealed." (PMID 24565034, 2013). "However, among the overlapped DE genes, we identified upregulation of genes encoding several markers typically overexpressed in ovarian cancer: cyclin E1 (Ccne1), RAD51-associated protein 1 (Rad51ap1), osteopontin (Spp1) and its signaling receptor, Cd44." (PMID 40642792, 2025). "Increased cyclin E expression, either by CCNE1 gene amplification, copy-number gain, or elevated protein expression, is associated with poor clinical outcomes and resistance to DNA-damaging drugs in ovarian cancer." (PMID 39695768, 2024). "Patient-derived xenograft models of BRCA-wildtype and CCNE1-amplified platinum-resistant ovarian cancer, which are associated with increased baseline activation of ATR/CHK1, demonstrated tumor reduction and a significant increase in OS when treated with the combination of PARPi and ATRi." (PMID 38894867, 2024). "In ovarian cancer, the near mutual exclusivity of homologous recombination pathway mutations and CCNE1 amplification generally results in resistance to platinum-based cytotoxic chemotherapies and ineffective Poly (Adenosine Diphosphate (ADP)-Ribose Polymerase (PARP) inhibition." (PMID 35792986, 2022). "Survival analysis found that CEP55 and CCNE1 may be associated with the prognosis of ovarian cancer." (PMID 34734085, 2021). "Looking also at the genomic level, a high-resolution genome-wide study of copy number variations in 118 ovarian cancer patients revealed the association of 19q12 amplification, which contains the cyclin E1 gene (CCNE1), with failure of primary treatment and worse survival." (PMID 32804260, 2020). "Furthermore, a growing body of evidence has demonstrated that increased cyclin E1 1 levels are associated with malignancies, such as ovarian cancer, and elevated cyclin E1 expression is a poor prognostic factor in lung adenocarcinoma patients." (PMID 33574763, 2020). "Amplification of CCNE1 is associated with poor outcome in gastric, breast, and ovarian cancer." (PMID 31164161, 2019). "Cyclin E1 overexpression is associated with increased “life time ovarian cycles” and ovarian cancer development is implicated with “incessant ovulation hypothesis”." (PMID 30581772, 2018). "To investigate whether the status of elevated CCNE1 expression could be linked to tumorigenic behaviors of ovarian cancer cell lines, we first assessed cell growth of these cell lines." (PMID 26204491, 2015). "Having identified CCNE1 as a critical driver within the 19q12 amplicon in ovarian cancer, we reasoned that other mutations elsewhere in the genome might interact with Cyclin E1 or be associated with drug resistance." (PMID 21103391, 2010).
ovarian carcinoma (continued). "The identification of outliers from functional genomic data also helps to uncover potential indications and predictive biomarkers associated with candidate targets (e.g. ovarian cancer and CCNE1 amplification for CDK2 inhibitors) that may guide the development of precision medicine strategies." (PMID 27296290, 2016). "The significant correlations between responsiveness to DL78 and high DNA copy number or CCNE1 expression further supported ovarian cancer as a suitable model to study DL78." (PMID 41173942, 2025). "Integrative single-cell and spatial transcriptomic analyses revealed subtype-specific roles of CCNE1 in ovarian cancer." (PMID 41331376, 2025). "CCNE1 amplification was detected in 8.40% of all patients, with the highest rates in patients with ovarian cancer (8.01%) and endometrial cancer (5.06%)." (PMID 41331376, 2025). "Cyclin E1 participates in many aspects of tumorigenesis, and dysregulation of cyclin E1 has been documented in ovarian cancers, breast cancer, and many other cancer types." (PMID 40959067, 2025). "Here, we evaluated the efficacy of the PLK1 inhibitor, volasertib, and the WEE1 inhibitor, adavosertib, along with the biomarker potential of cyclin E1 in ovarian cancer cells." (PMID 39994376, 2025). "Ovarian cancers (OVCAs) and endometrial cancers (EMCAs) with CCNE1-amplification are often resistant to standard treatment and represent an unmet clinical need." (PMID 40169546, 2025). "Our analysis revealed that CCNE1 amplification occurred in 8.01% of ovarian cancer patients, with the highest frequency observed in carcinosarcoma patients (12.46%), followed by high-grade serous carcinoma patients (HGSOC patients, 9.84%)." (PMID 41331376, 2025). "Ovarian cancers (OVCAs) and endometrial cancers (EMCAs) with CCNE1-amplification are often resistant to standard of care treatment and represent an unmet clinical need." (PMID 38410486, 2024). "For example, CCNE1 amplification was correlated with shorter relapse-free survival in patients with ovarian carcinomas treated with platinum-based chemotherapy." (PMID 39695768, 2024). "In a clear cell ovarian cancer study, cyclin E1 overexpression was observed in 23.3% of tumours and associated with poor survival outcomes." (PMID 38612869, 2024). "The oncogene CCNE1 is often upregulated or amplified in cancers such as osteosarcoma, lung, and ovarian cancers, while the tumor suppressors p21 and p27, frequently lost in various cancers, inhibit CCNE1 to block cell cycle progression to the S-phase." (PMID 39795950, 2024). "provided a preclinical rationale for the use of HDAC inhibitors (HDACi) to reduce HRR in HRP ovarian cancer, including CCNE1-amplified tumors, as a means to enhance PARPi activity." (PMID 38894867, 2024). "High levels of Cyclin E1 together with high levels of genetic instability can serve as markers for expanding the use of RS targeted drugs beyond breast and ovarian cancers." (PMID 38279263, 2024). "For instance, the overexpression of CCNE1 in ovarian cancer has been shown to promote genomic instability through its interaction with CDK2, which accelerates the cell cycle and impairs DNA repair mechanisms." (PMID 39591374, 2024). "Our study found that a subset of breast and ovarian cancer cell lines with CCNE1 amplification were sensitive to KIF18A inhibition but resistant to CDK4–CDK6 inhibition." (PMID 38151625, 2024).